ZNRF3 (zinc and ring finger 3)
Diseases named in the same sentence as ZNRF3 in open-access papers (continued):
Sharing a sentence is not in itself a finding about the gene and the disease.
glioma (3 papers, 2021 to 2026). A benign or malignant brain and spinal cord tumor that arises from glial cells (astrocytes, oligodendrocytes, ependymal cells). "Co-expression analysis showed that ZNRF3 expression level was negatively associated with RMRP expression in glioma tissues." (PMID 34657141, 2021). "Moreover, RMRP loss inhibited β-catenin expression by up-regulating ZNRF3 in glioma cells." (PMID 34657141, 2021). "Given the vital roles of ZNRF3 in Wnt/β‐catenin signaling and cancer progression, further investigations on ZNRF3 regulatory mechanisms can deepen our understanding of the pathogenesis of glioma." (PMID 34657141, 2021). "Our outcomes disclosed that RMRP knockdown led to the remarkable increase of ZNRF3 mRNA and protein expression and ZNRF3 mRNA stability in glioma cells." (PMID 34657141, 2021). "In other words, RMRP knockdown inhibited glioma cell proliferation, facilitated glioma cell apoptosis, and weakened the resistance of glioma cells to TMZ through up-regulating ZNRF3." (PMID 34657141, 2021). "Differential expression analysis revealed that ZNRF3 expression was notably down-regulated in glioma tissues versus normal tissues." (PMID 34657141, 2021). "Next, ZNRF3 was screened out based on differential expression and co-expression analyses for glioma and normal brain tissue data in the TCGA and GTEx databases and bioinformatics analysis." (PMID 34657141, 2021). "Molecular mechanism investigations revealed that RMRP exerted its functions by reducing ZNRF3 expression and ZNRF3 mRNA stability via IGF2BP3 in glioma." (PMID 34657141, 2021). "In a word, these outcomes showed that RMRP knockdown promoted ZNRF3 expression and improved ZNRF3 mRNA stability in glioma cells." (PMID 34657141, 2021). "In summary, these data revealed that ZNRF3 knockdown weakened the effects of RMRP depletion on glioma cell proliferation, apoptosis, and TMZ resistance." (PMID 34657141, 2021). "Moreover, bioinformatics analysis by the Ualcan database disclosed that glioma patients with low ZNRF3 expression had a poor prognosis." (PMID 34657141, 2021). "Additionally, ZNRF3 downregulation markedly weakened the effects of RMRP knockdown on glioma cell proliferation, apoptosis, and TMZ resistance." (PMID 34657141, 2021). "RMRP exerted its functions by down-regulating ZNRF3 in glioma cells." (PMID 34657141, 2021). "Our results showed that ZNRF3 knockdown promoted β‐catenin expression in glioma cells." (PMID 34657141, 2021). "Hence, we further investigated whether the RMRP/ZNRF3 axis could regulate the Wnt/β‐catenin signaling pathway in glioma cells." (PMID 34657141, 2021). "Another study found that the interaction between the lncRNA-RMRP/ZNRF3 axis and Wnt/β-catenin signaling regulates TMZ resistance in glioma." (PMID 36425564, 2022). "In conclusion, RMRP/ZNRF3 axis and Wnt/β-catenin signaling formed a positive feedback loop to regulate TMZ resistance in glioma." (PMID 34657141, 2021). "Results showed that IGF2BP3 loss led to the notable reduction of ZNRF3 level enriched by Ago2 antibody in U251 cells, suggesting that IGF2BP3 knockdown weakened the interaction of ZNRF3 and RISC in glioma cells." (PMID 34657141, 2021). "Thus, we further investigated whether RMRP could regulate ZNRF3 expression in glioma." (PMID 34657141, 2021). "Moreover, ZNRF3 depletion abolished the inhibitory effect of RMRP knockdown on cell survival in TMZ-treated parental glioma cells (U251 and LN229) and TMZ-resistant glioma cells (U251/TMZ and LN229/TMZ)." (PMID 34657141, 2021). "Moreover, we demonstrated that RMRP/ZNRF3 axis and Wnt/β‐catenin signaling pathway could form a positive feedback loop to regulate TMZ resistance in glioma." (PMID 34657141, 2021).
osteosarcoma (3 papers, 2017 to 2021). A usually aggressive malignant bone-forming mesenchymal neoplasm, predominantly affecting adolescents and young adults. "Up-regulation of miR-146b-5p was found in osteosarcoma tissues, and it promoted proliferation, migration and invasion through inhibiting ZNRF3 in osteosarcoma cells." (PMID 28404923, 2017).
adrenal hyperplasia (2 papers, 2015 to 2022). "Among these are somatic mutations of PKA catalytic subunit alpha gene (PRKACA) in ACA, germline, and somatic mutations of armadillo repeat containing 5 gene (ARMC5) in primary bilateral macronodular adrenal hyperplasia and somatic alterations of the E3 ubiquitin ligase gene ZNRF3 in ACC." (PMID 26106367, 2015). "Together, these data show that Znrf3 ablation induces sustained recruitment of IBA-1+ and MERTKhigh macrophages, which results in phagocytic clearance of preneoplastic steroidogenic cells and regression of adrenal hyperplasia in male mice." (PMID 36240276, 2022).
breast carcinoma (2 papers, 2024). "In MDA-MB-231, a breast cancer cell line with moderate levels of ZNRF3/RNF43, overexpression of either ZNRF3 or RNF43 substantially reduced EGFR protein levels." (PMID 38260423, 2024).
intestinal tumors (2 papers, 2022 to 2025). "Mouse genetic studies have shown that the simultaneous disruption of Rnf43 and Znrf3 in the intestine results in Wnt ligand‐independent growth and development of intestinal tumors through Wnt signaling activation." (PMID 35040131, 2022).
metastatic prostate carcinoma (2 papers, 2021 to 2022). A carcinoma that arises from the prostate gland and has spread to other anatomic sites. "GSEA of Gene Ontology (GO) pathways revealed enrichment of cell cycle progression gene sets in tumors harboring ZNRF3 loss, which validated in two independent cohorts of both localized and metastatic prostate cancer." (PMID 34716314, 2021). "Future investigations exploring the role of clinically relevant genetic aberrations in RNF43 and ZNRF3 during primary and metastatic prostate cancer will be important to ascertain their impact on Wnt signaling." (PMID 35204808, 2022). "In regard to ZNRF3, 1.8% of metastatic prostate cancer patients are reported to harbor genetic alterations, in comparison to just 0.2–0.44% of patients with the primary disease." (PMID 35204808, 2022). "Interestingly, ZNRF3 deep deletions are also observed in primary and metastatic prostate cancer (≤2%), potentially promoting Wnt signaling via the stabilization of FZD receptors and Wnt co-receptors at the plasma membrane." (PMID 35204808, 2022).
thyroid cancer (2 papers, 2017 to 2023). "Through targeting ZNRF3, miR-146b-5p facilitates thyroid cancer metastasis and triggers EMT." (PMID 36882799, 2023).
acne (1 paper, 2024). An inflammatory process of the sebaceous glands which is characterized by comedones, nodules, papules and/or pustules on the skin. "Three novel acne associated genes are also involved in the Wnt signaling pathway: ZNRF3 and KREMEN1 from 22q12.1 and LGR5 from 12q21.1." (PMID 36922633, 2024). "We detected significant enrichment of TSPAN8, along with other novel genes (LGR5, ZNRF3, KREMEN1) and several known acne susceptibility genes, for the GO biological processes gene sets “GO negative regulation of response to stimulus” and “GO regulation of response to stress”." (PMID 36922633, 2024).
Adrenal insufficiency (1 paper, 2024). Insufficient production of steroid hormones (primarily cortisol) by the adrenal glands. "This may partly support a causal link between ZNRF3 and the adrenal insufficiency observed in the two individuals in our cohort who each harbored a large in-frame deletion in ZNRF3 (I-10 and I-11)." (PMID 39168120, 2024). "Although we consider these variants candidates for causing adrenal insufficiency, congenital heart defects, and nephrotic syndrome, they remain VUS until further proof, but at least suggests that haploinsufficiency of ZNRF3 is not causing neurodevelopmental problems." (PMID 39168120, 2024).
age (1 paper, 2025). A temporal measurement of the time period elapsed since an identifiable point in the life cycle of an organism. "By identifying miR-668-5p as a regulator of osteoblast function that targets ZNRF3 to activate Wnt/beta-catenin signaling, our study provides a mechanistic basis for considering miR-668-5p in the development of novel strategies to mitigate chemotherapy-associated and age-related bone deterioration." (PMID 41220584, 2025).
Anonychia (1 paper, 2013). Aplasia of the nail. "Other interface mutants in Fu1, including the anonychia-associated mutations R65W, Q70R and G72R, as well as N50R, each exhibited weakened signalling ability that correlated with reduction in binding to ZNRF3." (PMID 24225776, 2013).
blood pressure (1 paper, 2023). "The TCF7L2 risk genotype was associated with a long duration of diabetes and high diastolic blood pressure, the ZCWPW2 risk genotype was associated with increased glycosylated hemoglobin, and the ZNRF3 risk genotype was associated with an increased urinary microalbumin-to-creatinine ratio." (PMID 38189041, 2023).
breast tumors (1 paper, 2022). "With regard to activation of the canonical Wnt pathway, we observed that RSPO3‐driven breast tumors expressed the Wnt/β‐catenin target genes Axin2, Wif1, Znrf3, and Ctnnb1 itself, however at significantly lower levels than their WNT1‐driven counterparts." (PMID 36106661, 2022).
diabetes (1 paper, 2023). "For example, the TCF7L2 risk genotype was associated with a long duration of diabetes and high diastolic blood pressure, the ZCWPW2 risk genotype was associated with a high level of HbA1c, and the ZNRF3 risk genotype was associated with an elevated urinary microalbumin-to-serum ratio." (PMID 38189041, 2023).
diabetic nephropathy (1 paper, 2023). "Data mining of the published microbial quantitative trait loci indicated that the risk genotypes of rs2294239 (ZNRF3) and rs3747113 (SPECC1L) in diabetic nephropathy were correlated with the abundance of Lactococcus, which is a microorganism that is beneficial to the human body." (PMID 38189041, 2023).
hypercortisolism (1 paper, 2021). "Although all of them presented with hypercortisolism at initial presentation and died due to ACC (OS 7, 36, and 12 months, respectively), they presented with variable expression of ATRX (score 2, 0, and 0, respectively) and variable expression of ZNRF3 (score 3, 2, and 5, respectively)." (PMID 33513905, 2021).
hyperplasia (1 paper, 2024). An abnormal increase in the number of cells in an organ or a tissue with consequent enlargement. "It has been shown that in mice Znrf3 is expressed throughout the adrenal cortex during development, and its conditional knockout resulted in adrenal hyperplasia with a reduced plasma concentration of corticosterone." (PMID 39168120, 2024).
leukemia (1 paper, 2013). A malignant (clonal) hematologic disorder, involving hematopoietic stem cells and characterized by the presence of primitive or atypical myeloid or lymphoid cells in the bone marrow and the blood. "MN1 and NF2 have previously been implicated in the development of leukemia and solid tumors, and ZNRF3 and KREMEN1 are inhibitors of the Wnt/beta-catenin signaling pathway." (PMID 24236197, 2013).
liver cancer (1 paper, 2022). An epithelial or non-epithelial malignant neoplasm that arises from the liver. "Here we find that loss of RNF43/ZNRF3 predisposes to liver cancer by controlling liver lipid metabolic ground-state and the balance between proliferation/differentiation in hepatocytes." (PMID 35039505, 2022). "Here, the authors show that RNF43/ZNRF3 alterations predispose to liver cancer by controlling the differentiation and lipid metabolic state of hepatocytes." (PMID 35039505, 2022). "Our observations imply that RNF43/ZNRF3 predispose to liver cancer, at least in part, by altering the hepatocyte metabolic ground-state while, in parallel, preventing the tissue from completely regenerating upon damage." (PMID 35039505, 2022). "Our results imply that RNF43/ZNRF3 predispose to liver cancer by controlling the proliferative/differentiation and lipid metabolic state of hepatocytes." (PMID 35039505, 2022). "Upon injury, Rnf43/Znrf3 deletion results in defective hepatocyte regeneration and liver cancer, caused by an imbalance between differentiation/proliferation." (PMID 35039505, 2022). "Our findings might aid on the management of those RNF43/ZNRF3 mutated individuals at risk of developing fatty liver and/or liver cancer." (PMID 35039505, 2022). "Interestingly, both genes need to be depleted in mice to account for the development of liver cancer; however, in humans, a single ZNRF3 mutation was a significant prognostic biomarker." (PMID 35039505, 2022). "We next performed differential expression analysis of the livers of patients harbouring WNT mutations (WNT), RNF43 and ZNRF3 (R&Z) and RNF43 or ZNRF3 (RorZ) compared to liver cancer patients with WT alleles for these." (PMID 35039505, 2022). "In summary, our studies provide a framework to start to understand the role of the tumour suppressors RNF43/ZNRF3 in liver cancer." (PMID 35039505, 2022). "To determine the relevance of our findings in human liver cancer, we next assessed the effect of RNF43/ZNRF3 mutations in human primary liver tumours taking advantage that the projects LIRI-JP and LICA_FR from the ICGC collection, contained genomic and expression data of the same tumours." (PMID 35039505, 2022). "In summary, our results indicated that human liver cancer patients bearing ZNRF3 and/or RNF43 mutations present altered liver lipid metabolism, in agreement with our findings in the Rnf43/Znrf3 mutant mouse model, and identified ZNRF3 and/or RNF43 as potential prognostic biomarkers for liver cancer." (PMID 35039505, 2022). "Interestingly, ZNRF3 mutant liver cancer patients present poorer prognosis, altered hepatic lipid metabolism and steatohepatitis/NASH signatures." (PMID 35039505, 2022).
lung adenocarcinoma (1 paper, 2021). A carcinoma that arises from the lung and is characterized by the presence of malignant glandular epithelial cells. "We tested an alternative lung adenocarcinoma cell line, H3122, and inhibiting MET with Crizotinib reduced mature LRP6, an effect that was almost abolished when ZNRF3/RNF43 where siRNA-inhibited." (PMID 34590584, 2021). "To screen these 18 PTKs, we utilized H1703 human lung adenocarcinoma cells harboring doxycycline (Dox)-inducible ZNRF3-HA (TetOn ZNRF3-HA) to overcome poor transfection efficiency of this cell line as well as the general lack of antibodies against endogenous ZNRF3." (PMID 34590584, 2021).
Macrocephaly (1 paper, 2024). Occipitofrontal (head) circumference greater than 97th centile compared to appropriate, age matched, sex-matched normal standards. "establish germline missense variants in the tumor suppressor gene ZNRF3 as a cause of neurodevelopmental disorders (NDDs) with microcephaly or macrocephaly, depending on the functional/domain-specific effects of the variants on Wnt/β-catenin signaling." (PMID 39168120, 2024). "We have identified de novo deleterious missense variants in the gene ZNRF3 in affected individuals with mirror brain phenotypes: microcephaly and macrocephaly." (PMID 39168120, 2024). "Unlike WDFY3-associated macrocephaly where Wnt/β-catenin signaling was downregulated, Wnt/β-catenin signaling was enhanced for missense variants in ZNRF3 from the macrocephaly affected individuals, while decreased for the ZNRF3 missense variant from the microcephaly affected individual." (PMID 39168120, 2024).
metastatic carcinoma (1 paper, 2022). A carcinoma which has spread from the original site of growth to another anatomic site. "In contrast with males, female Znrf3 cKO adrenals progress from hyperplasia at 4 weeks to development of full-fledged metastatic carcinomas at 78 weeks." (PMID 36240276, 2022).
microcephaly (1 paper, 2025). A congenital or acquired developmental disorder in which the circumference of the head is smaller than normal for the person's age and sex. "Conversely, microcephaly-associated ZNRF3 variants localize to the RSPO-binding domain, conferring resistance to RSPO inhibition and resulting in hyperactive Frizzled degradation, diminished Wnt signaling, reduced NSPC proliferation, and microcephaly." (PMID 41283518, 2025).
non-alcoholic steatohepatitis (1 paper, 2023). "Mutations in RNF43 and ZNRF3 altered lipid metabolism specifically in unsaturated fatty acids, acyl-CoA biosynthesis and non-alcoholic steatohepatitis (NASH)." (PMID 36768732, 2023). "Likewise, mutations in RNF43 and ZNRF3 have been reported in altered lipid metabolism, specifically in unsaturated fatty acids, acyl-CoA biosynthesis and non-alcoholic steatohepatitis (NASH)." (PMID 36768732, 2023).
Osteoblastoma (1 paper, 2013). A rare benign bone-forming neoplasm usually arising from the spine. "Here, we hypothesized that if loss of genes such as ZNRF3 and KREMEN1 and subsequent activation of beta-catenin is important for osteoblastoma development we would find high expression levels of genes activated by Wnt/beta-catenin in these tumors." (PMID 24236197, 2013).
ovarian tumors (1 paper, 2024). "When BRCA2mt ovarian tumors were compared with BRCA1mt tumors, eight genes (NOTUM, SFRP5, RNF43, ZNRF3, DKK1, DKK4, NKD1, and AXIN2) that negatively regulate Wnt signaling were upregulated in BRCA2mt tumors." (PMID 39028933, 2024).